CTCF (CCCTC-binding factor)
Diseases named in the same sentence as CTCF in open-access papers (continued):
Sharing a sentence is not in itself a finding about the gene and the disease.
schizophrenia (11 papers, 2014 to 2025). A major psychotic disorder characterized by abnormalities in the perception or expression of reality. "A separate genetic study determined an association between Single-nucleotide polymorphism (SNPs) in the genomic vicinity of CTCF and schizophrenia (SCZ)." (PMID 35379308, 2022). "Remarkably, schizophrenia disease risk variants often overlap anchors of CTCF–CTCF loops present in induced pluripotent stem cells‐derived neuronal cells." (PMID 35993175, 2022). "In addition to germline variants in CTCF being associated with neurodevelopmental disorder, genome-wide association studies (GWAS) have also identified CTCF variants that are associated with schizophrenia." (PMID 37324587, 2023). "In a study that used an integrated pathway-based approach to evaluate more than 10,000 individuals of European ancestry in conjunction with data from the Psychiatric Genomics Consortium Schizophrenia, certain mutations in the CTCF locus identified as a strong risk factor for schizophrenia." (PMID 36447271, 2022). "If it formed a CTCF consensus, the possibility is considered that the minor allele frequency is lower than in the healthy control at the female W4 (rs319471, minor allele: T), thus it is possible that the CTCF-binding activity is higher in schizophrenia." (PMID 29309433, 2018). "However, the number of CTCF binding–disrupting SNPs (observed in this study) were not significantly different from random SNPs (P > 0.05, 1000 simulations), implying that the frequent disruption of CTCF by schizophrenia risk SNPs may be due to random effect." (PMID 30737407, 2019). "The study detected strong association between SNPs in the genes CTCF and CACNB2 and schizophrenia, using a gene pathway-based approach." (PMID 35379308, 2022). "For two genes, i.e. CTCF and CACNB2, evidence for association with schizophrenia was available (at the gene-level) in both the discovery study and published data from the Psychiatric Genomics Consortium schizophrenia study." (PMID 24901509, 2014). "For two genes, i.e., CTCF and CACNB2, evidence for association with schizophrenia was available (at the gene level) in both the discovery study and the published data from the Psychiatric Genomics Consortium schizophrenia study." (PMID 35328011, 2022). "Binding of CTCF and POLR2A were frequently disrupted by schizophrenia risk SNPs." (PMID 30737407, 2019). "In particular, CTCF, CACNB2, and ARL5B, i.e. genes involved in chromatin modulation, calcium channel signaling and membrane transport, respectively, were highlighted as candidate genes for schizophrenia risk." (PMID 24901509, 2014). "Several of the SNVs assigned to CTCF and CACNB2 have potential functional consequences, and a gene in close proximity to CACNB2, i.e., ARL5B, was identified as a potential gene of interest in schizophrenia and depressive disorder comorbidity." (PMID 35328011, 2022).
cervical carcinoma (8 papers, 2010 to 2024). A carcinoma arising from either the exocervical squamous epithelium or the endocervical glandular epithelium. "A related study reported that both CCND1 and CTCF were identified as significant mutated genes in cervical cancer." (PMID 39623397, 2024). "Once the median value of U2OS was divided by the one of HeLa Kyoto, we found that the total amount of CTCF in the osteosarcoma cell line is double the one of cervical cancer cells." (PMID 35409255, 2022). "Like in various human cancer cell lines and primary tumors, including HeLa cells and a cervical carcinoma, we also observed increased methylation of the first CTCF site in HPV-transformed cell lines and cervical SCC." (PMID 20534141, 2010). "We hypothesize that the lower effect seen in the CTCF-depleted osteosarcoma cells compared to the cervical cancer cells reflects a fact that is often neglected: that the endogenous levels of CTCF are significantly different in the two cell lines." (PMID 35409255, 2022). "Notably, our novel identification of CCND1 and CTCF as SMGs put the converging role of cell cycle progression in HPVU cervical cancer into clear perspective." (PMID 34572780, 2021). "It is possible that aberrant methylation in some CpGs in the IGF2/H19 imprinted domain such as the intron 3 CTCF site may be influencing loss of imprinting and the exclusive usage of IGF2 promoter 1, inducing IGF2 overexpression, as has been previously shown in cervical carcinomas." (PMID 23775149, 2014).
Obesity (8 papers, 2015 to 2025). Accumulation of substantial excess body fat. "Several obesity-associated SNPs may affect “transcription factories”, clusters of gene promoters and their enhancers that interact in three-dimensional space and are brought together by DNA-binding proteins such as CTCF." (PMID 26449484, 2015). "Analysis of chromatin accessibility in the sperm of the F1-F6 generations exhibits alterations at sites containing binding motifs for CTCF at two cis-regulatory elements of the FTO gene that correlate with the transmission of obesity." (PMID 39125332, 2024). "This transmission of obesity correlates with epigenetic changes in sperm showing alterations in sites containing binding motifs for the CCCTC-binding factor (CTCF) of the Fto gene." (PMID 37134142, 2023). "When pregnant F0 mouse dams were exposed to BPA, the obesity phenotype was inherited through the F6 generation offspring depending on the status of CTCF." (PMID 34975759, 2021). "The deleted CTCF-element in intron 8 in BFMI, I8∆1, and I8∆2 may be responsible for reducing Bbs7 transcription levels, which might cause obesity by influencing fat deposition." (PMID 34910225, 2022). "The authors analyzed F1-F6 generation sperm and concluded that the development of obesity was dependent on the binding of CTCF at two enhancer regions of the Fto gene and that eliminating the CTCF binding site in this gene also eliminated the obese phenotype despite BPA exposure." (PMID 34975759, 2021).
Wilms’ tumour (8 papers, 2004 to 2025). "In all seven samples from the child’s tumour, we found a likely disruptive somatic CTCF variant of the remaining allele and detected associated hypermethylation of H19 (thought to be the Wilms tumour promoting effect of CTCF loss)." (PMID 39665570, 2025). "We included R339W as a positive control as it was first identified in Wilms’ tumour as a potential ‘change-of-function’ mutation that abrogated DNA binding to a subset of CTCF sites regulating genes involved in cell proliferation." (PMID 34657170, 2021). "Loss of heterozygosity (LOH) at 16q22 can lead to CTCF haploinsufficiency and IGF2 up-regulation in Wilms’ tumours." (PMID 30513694, 2018).
acute myeloid leukemia (7 papers, 2017 to 2024). Acute myeloid leukemia (AML) is a group of neoplasms arising from precursor cells committed to the myeloid cell-line differentiation. "Consistent with this, we find that BRD9 is essential for the development and maintenance of acute myeloid leukemia (AML) as its loss remarkably promotes myeloid differentiation with open chromatin at CTCF sites." (PMID 38102116, 2023). "Many cancer-related pathways were enriched in H3K27ac -/+ common CTCF loop anchors, such as “Pancreatic cancer” and “Acute myeloid leukemia”." (PMID 36997534, 2023). "For example, somatic mutations in the eight genes that comprise the cohesin ring (SMC1A, SMC3, STAG1, STAG2, RAD21) and the cohesin-ring support genes (NIPBL, MAU2, WAPL, PDS5A, PDS5B) and CTCF are frequently found in many cancer types and are especially common in acute myeloid leukemia (AML)." (PMID 36171609, 2022).
asthma (7 papers, 2015 to 2023). "In contrast, five SNPs in high LD with the asthma-associated lead SNPs overlapped with a region of open chromatin and CTCF, cohesin and ZNF binding, delineating a discrete 5 kb region (chr9: 6,194,500–6,199,500, hg19)." (PMID 34675193, 2021). "Further, we discovered that an asthma-risk SNP in this enhancer favours the binding of CTCF (rs4065275), while in contrast another linked SNP downstream of this site prevented CTCF binding (rs12936231), leading to alteration of CTCF-binding patterns in the locus." (PMID 27848966, 2016). "Thus, the asthma-risk haploblock harbours linked SNPs that switch the binding site of CTCF from the ZPBP2 to the ORMDL3 intronic region." (PMID 27848966, 2016). "CTCF was also found to be recruited in asthma risk-related SNPs of the ORMDL3 gene and increased the activity of its enhancer in naïve CD4 T cells, which was essential for the repression of Il2 expression in the same cell type, a mechanism that may contribute to asthma progression." (PMID 35812421, 2022). "Specific to asthma, differential expression at the ZPBP2/GSDMB/ORMDL3 locus was identified resulting from allele-specific chromatin remodeling mediated by CTCF." (PMID 29228930, 2017). "Collectively, our analyses reveal a new link between TET1, CTCF and enhancers that future studies should expand on to improve our understanding of the role of TET1 in responding to environmental exposures linked to asthma." (PMID 38168374, 2023). "Concurrent increase and decrease in the expression of neighboring genes in relation to a susceptibility haplotype for childhood asthma were previously shown for the same genomic region, possibly due to differential associations between the CCCTC-binding factor (CTCF) and different haplotypes." (PMID 26484354, 2015).
heart failure (7 papers, 2019 to 2026). Inability of the heart to pump blood at an adequate rate to meet tissue metabolic requirements. "Studies using an in vivo loss-of-function mouse model have revealed that CTCF depletion is enough to induce heart failure." (PMID 35891791, 2022). "Our data further suggest that CTCF-mediated chromatin interactions are affected in terminal heart failure in CM." (PMID 41526351, 2026). "It has been reported that cardiomyocyte-specific depletion of CTCF, an essential factor for chromatin interactions, leads to spontaneous and sustained cardiac dilation as well as the heart failure stress response." (PMID 36653336, 2023). "CTCF gene is essential for cardiogenesis and to inhibit cardiomyocytes apoptosis, and can be applied as a therapeutic target for the treatment of heart failure in future." (PMID 35529472, 2022). "CTCF is downregulated in patients with heart failure, and deletion of Ctcf in mice leads to heart failure and 3D chromatin reorganization, including 99% loss of chromatin loops, TAD disruption, and A/B compartment switching in nearly 4% of the genome." (PMID 36539553, 2022). "CTCF knock-out mice not only mirrored the chromatin remodeling findings of the TAC heart failure mice but also recapitulated the cardiac dysfunction seen in heart failure." (PMID 31346662, 2019). "Not surprisingly, CTCF knock-out mice did not reveal changes in H3K27me3 nor in H3K4me3, indicating the effects occurred via an alternative epigenetic mechanism to histone modifications and illustrating the critical role CTCF plays in chromatin regulation and heart failure." (PMID 31346662, 2019).
latent infection (7 papers, 2010 to 2024). "Here, we show that latent infection of monocytes by HCMV increases CTCF expression and that the latency-associated viral gene US28 is sufficient for this upregulation." (PMID 34042564, 2021). "The locations of the individual insulators are interesting; they flank the LAT and each of the IE genes, suggesting that individual CTCF insulators are key elements in maintaining IE gene silencing during the latent infection." (PMID 39374265, 2024). "We show that latent infection drives increased CTCF occupancy on the enhancer region of these genes, and that US28 expressed in isolation in myeloid cells is able to drive decreased S100A8 and S100A9 secretion." (PMID 34042564, 2021). "Recently, the role of CTCF in human cytomegalovirus (HCMV) latent infection altering gene expression has been established." (PMID 34940755, 2021). "Of the various sites on the HSV-1 genome that bind CTCF during latent infection, CTRL2 has been of particular interest due to its position between the transcriptionally active LAT promoter and the silenced ICP0 promoter (64, –, 66)." (PMID 29437926, 2018). "Results from related herpesviruses, EBV and KSHV, have also indicated that CTCF has a complex role in promoting latent infection." (PMID 29437926, 2018). "Our findings also indicate that protection of Qp by CTCF is essential for EBV genome stability during long-term latent infection." (PMID 20730088, 2010). "CTCF binds at the CTRL2 sites during latent infection but is lost during reactivation, and this site has been hypothesized to regulate distinct expression from the adjacent genetic elements (64, –, 66)." (PMID 29437926, 2018). "In support of this hypothesis, CTCF has been shown to co-localize with cohesin in the KSHV episome on a region of the major latency control transcript during latent infection." (PMID 26154016, 2015). "Taken together, these analyses suggest that CTCF interacts with the lytic HSV-1 genome when HSV-1 genomes are actively being transcribed, and that these CTCF sites may be different than those observed during latent infection or in the early stages of reactivation." (PMID 28045091, 2017). "Our view is that the role of CTCF during latent and lytic HCMV infection should now also be expanded using comprehensive analyses of chromatin architecture, and CTCF/cohesin interactions during HCMV lytic and latent infections, including reactivation." (PMID 34042564, 2021). "Therefore, CTCF, LAT, and ICP0 may all be acting to promote the correct form of viral chromatin so that a poised latent infection is established and maintained and reactivation can take place at the appropriate time." (PMID 29437926, 2018).
liver cancer (7 papers, 2015 to 2021). An epithelial or non-epithelial malignant neoplasm that arises from the liver. "The association between ARID1A/BRG1 and CTCF/RAD21 was affirmed in human liver cancer cell lines in vivo." (PMID 34689165, 2021). "The strongest impact of mutation on functional CTCF sites in the current data was observed in liver cancer samples, which showed the most dramatic increase in numbers of mutations observed." (PMID 27490693, 2016). "We aligned ChIP-seq data of CTCF from human liver cancer cell HepG2 to HG19_plus_rDNA and we have discovered that in human hepatic cancer cells, CTCF was highly enriched at the 3′ end of human ribosomal DNA just upstream of TSS." (PMID 26657029, 2015). "Altogether, our studies showed for the first time a high-resolution map of histone modification marks and CTCF at rDNA in human liver cancer cell, and give evidence for future research of chromatin-mediated regulation of rDNA in liver cancer." (PMID 26657029, 2015). "We also report the presence of CTCF, an insulator-binding protein, at the rDNA space promoter in human liver cancer cell." (PMID 26657029, 2015). "Here we aligned the ChIP-seq data of histone modification markers and CTCF to the human genome assembly which contains a single rDNA repeat in human liver cancer cell and validated their distribution with ChIP-QPCR." (PMID 26657029, 2015). "Taken together, our study compared the distribution of histone modification markers and CTCF at rDNA in human liver cancer cell with that in normal human liver cells." (PMID 26657029, 2015). "It is hit by five mutations in liver cancer, which also overlap a TFBS for CTCF (q = 0.1)." (PMID 29354286, 2018). "Furtherly, we studied whether UBF could affect histone modification markers and CTCF at rDNA in human liver cancer cell." (PMID 26657029, 2015). "TGF-β, together with the chromatin insulator CCCTC-binding factor (CTCF), epigenetically and transcriptionally regulate tumor promoter genes, including IGF2 and TERT, in TGF-β–defective mice and in human liver cancers." (PMID 33457451, 2020). "On the other hand, in a recent study, neither ectopic expression nor silencing of CTCF affected the proliferation of liver cancer cells and nasopharyngeal carcinoma cells, results that are consistent with the findings of the present study." (PMID 28977939, 2017). "Next we tested whether UBF can affect the distribution of CTCF on rDNA, and no change was found in the distribution of CTCF on rDNA after UBF depletion in human liver cancer cell HepG2." (PMID 26657029, 2015).
lymphoma (7 papers, 2014 to 2024). A malignant (clonal) proliferation of B- lymphocytes or T- lymphocytes which involves the lymph nodes, bone marrow and/or extranodal sites. "Recently, it was shown that CTCF insulators serve as putative cancer drivers in different tumors, including lymphomas." (PMID 34359791, 2021). "Previous work in lymphoma cells had indicated that cohesin components, including Rad21, but not CTCF, repress KSHV immediate-early gene expression." (PMID 24415941, 2014). "CTCF is essential for the proper regulation of gene expression, and the down-regulation of CTCF in the cluster group with shorter PFS is likely resulting in widespread disorganization of the chromatin structure and aberrant gene expression in the lymphomas of these patients." (PMID 39591314, 2024).
pancreatic cancer (7 papers, 2022 to 2025). "In pancreatic cancer, binding of CTCF to lncRNA PACERR was reported to increase histone acetylation, which enhanced transcription and promoted M2 polarization of tumor-associated macrophage." (PMID 40548301, 2025). "By utilizing a limited dataset of six epigenetic signals (CTCF, H3K27me3, H3K4me3, H3K9me3, H3K27ac, H3K36me3) from two types of pancreatic cancer cells, PANC-1 (primary) and Capan-1 (metastatic), EpiVerse inferred missing epigenetic tracks using Avocado, integrating these with experimental signals." (PMID 40221401, 2025). "In pancreatic cancer, CCCTC-binding factor (CTCF) cooperatively regulates histone lactylation and m6A modification through lncRNA FLG-AS1, activating the IGF2BP2/CSF1 axis to drive M2 polarization." (PMID 41459510, 2025). "CTCF‐knocked‐down HO‐8910 and SK‐OV‐3 cells showed a significant inhibition of proliferation and migration (p < 0.001), which was consistent with the role of RPL35A knockdown in pancreatic cancer cells." (PMID 38436544, 2024).
viral infection (7 papers, 2015 to 2024). "Overall, the role of CTCF in the context of viral infections is an area of active research, and further studies are needed to fully understand the mechanisms by which CTCF regulates viral gene expression and how viruses modulate CTCF activity." (PMID 37243174, 2023). "Interestingly, PARP1 plays a role in the infection of other DNA viruses, including HSV-1 and KSHV, which are also epigenetically regulated by CTCF, thus suggesting that PARP1 and CTCF interaction might be a common regulatory axis of viral infection." (PMID 37243174, 2023). "To determine if CTCF also restricted the assembly of non-permissive chromatin on the viral genome, we assayed the effect of CTCF depletion on the accumulation of the repressive histone mark H3K27me3 and heterochromatin mark H3K9me3 on HSV-1 DNA during viral infection." (PMID 28045091, 2017). "CTCF also interacted with viral non-structural protein nsp15, downregulated in cells infected with SARS-CoV-2 as well as in the lungs of COVID-19 patients, and decreased by IFN treatment and identified as a modulator of viral infection." (PMID 34940755, 2021).
autism (6 papers, 2018 to 2024). Persistent deficits in social interaction and communication and interaction as well as a markedly restricted repertoire of activity and interest as well as repetitive patterns of behavior. "Some patients with CTCF mutations are diagnosed with autism, which includes social deficits." (PMID 35379308, 2022).